EGR1 (early growth response 1)
Diseases named in the same sentence as EGR1 in open-access papers (continued):
Sharing a sentence is not in itself a finding about the gene and the disease.
papillary thyroid carcinoma (4 papers, 2014 to 2023). "EGR1/2 is involved in cell growth and apoptosis in different types of cancer and could inhibit tumor development, including Papillary Thyroid Carcinoma Cell Growth29." (PMID 37985782, 2023). "As far as the papillary thyroid carcinomas are concerned, FOS, FOSB and EGR1 genes were down-regulated, like CBX7, while SPP1, SPINK1 and STEAP1 were up-regulated." (PMID 24865347, 2014).
periodontitis (4 papers, 2021 to 2026). An acute or chronic inflammatory process that affects the tissues that surround and support the teeth. "Among these upregulated genes during periodontitis, Egr1, Atf3, and Zfp36 code for transcription factors that regulate expression of genes associated with control of inflammatory responses." (PMID 39588378, 2024). "The TFs involved are the two high-outdegree TFs, ETS1 and EGR1, which reveals that the TFs ETS1 and EGR1 play a crucial role in the invasion and activity of immune cells in periodontitis." (PMID 33841510, 2021). "Comparing the Average global expression profile of neutrophils from healthy PDL versus neutrophils from PDL with periodontitis revealed increased expression of genes such as Il1b, Il1rn, Cebpb, Colec12, Ptgs2, Zfp36, Egr1, Atf3, Csf1, and Lars2 in periodontitis." (PMID 39588378, 2024). "In addition to ETS1, our analyses also identified EGR1 (Early Growth Response 1) as MR in periodontitis." (PMID 37834287, 2023). "Three functional modules have been revealed and top TFs such as EGR1 and ETS1 have been shown to regulate the expression of periodontitis-related immune genes that play an important role in the formation of the immunosuppressive microenvironment." (PMID 33841510, 2021). "Within this group, both EGR1 and ETS1 played a key role in regulating the expression of crucial immune genes and forming the immunosuppressive microenvironment observed during the pathogenesis of periodontitis." (PMID 37834287, 2023).
renal cell carcinoma (4 papers, 2012 to 2021). "MAML1 acts cooperatively with EGR1 to activate EGR1-regulated promoters, which could also have implications for the development of renal cell carcinoma." (PMID 30466390, 2018). "Our findings suggest MAML1 may be a component of the transcriptional networks which regulate EGR1 target genes during nephrogenesis and could also have implications for the development of renal cell carcinoma." (PMID 23029358, 2012). "In renal cell carcinoma, down-regulation of CXXC4 by siRNA resulted in the up-regulation of some cellular proliferation related genes (FGF18, EGR1, and MYCN), the down-regulation of apoptosis inhibitor proteins BIRC7 and XAF1, and some other important tumor progression factors." (PMID 30042169, 2018).
rheumatoid arthritis (4 papers, 2009 to 2024). A chronic, systemic autoimmune disorder characterized by inflammation in the synovial membranes and articular surfaces. "The excess of EGR1 induced an increase of transcripts and protein of type I collagen in synovial fibroblasts from rheumatoid arthritis patients." (PMID 32121305, 2020).
skin cancer (4 papers, 2014 to 2023). "GRK2 also plays an important role in suppressing cell cycle progression, regulating early growth response 1 (EGR1) expression, and the progression of breast, gastric, and skin cancer by modulating GPCR signaling." (PMID 33806057, 2021).
systemic sclerosis (4 papers, 2011 to 2023). A chronic disorder, possibly autoimmune, marked by excessive production of collagen which results in hardening and thickening of body tissues. "The early growth response 1 (EGR1) is a central transcription factor involved in systemic sclerosis (SSc) pathogenesis." (PMID 37596660, 2023). "EGR1 expression is increased in biopsies of fibrotic skin and lung from patients with systemic sclerosis." (PMID 32121305, 2020). "The demonstrated involvement of EGR1 in this fibrotic disease identifies EGR1 as a pertinent target to control fibrosis in systemic sclerosis." (PMID 32121305, 2020). "EGR1 functions as a downstream mediator of TGF-β1 and is responsible for a SMAD-independent increase in collagen mRNA expression in systemic sclerosis." (PMID 25480529, 2014).
tubulointerstitial nephritis (4 papers, 2019 to 2024). "Egr-1 deficiency in primary renal tubuloepithelial cells isolated from mice could weakly respond to pro-inflammatory and pro-fibrotic stimuli ex vivo, and Egr1−/− mice with tubulointerstitial nephritis expressed less TNFα and CCL2." (PMID 38397780, 2024). "Egr-1 expression is upregulated in the kidneys with tubulointerstitial nephritis (TIN), and Egr-1-deficient mice are protected from TIN through reduced renal inflammation and fibrosis." (PMID 37762598, 2023).
type 2 diabetes (4 papers, 2019 to 2024). "Egr-1 plays a causal role in the development of type 2 diabetes." (PMID 39619154, 2024). "Beyond type 2 diabetes, which mainly affects older individuals, EGR1 has been used as a marker gene for childhood-onset type 2 diabetes." (PMID 39619154, 2024). "Hyperinsulinemia, a precursor symptom in the ontogenesis of type 2 diabetes mellitus (T2DM), is propelled by the transcriptional activation of PTP1B by the early growth response gene-1 (Egr-1), which, in turn, promotes insulin resistance in hepatic tissues." (PMID 39065585, 2024).
acute lymphoblastic leukemia (3 papers, 2020 to 2022). Leukemia with an acute onset, characterized by the presence of lymphoblasts in the bone marrow and the peripheral blood. "In acute lymphoblastic leukemia (ALL) EGR1 induction via suppression of HSP70 induces apoptosis and inhibits cell proliferation, whereas loss of EGR1 in these cells increased the proliferation and reduces apoptosis of ALL cells." (PMID 35923847, 2022). "In lymphoblastic leukemia, miR-181a can target and downregulate EGR1 which increases the proliferation and survival of leukemic cells leading to negative outcomes." (PMID 35923847, 2022). "Upregulation of miR-181a (a member of the miR-181 cluster) in Jurkat T-ALL cells (T-acute lymphoblastic leukaemia) reduced EGR1 (early growth response one) level, inducing G1/S cell-cycle progression and cell proliferation." (PMID 34440837, 2021).
adenoma (3 papers, 2021 to 2025). A neoplasm arising from the epithelium. "•Aldosterone-producing micronodules and adenomas show reduced EGR1 expression." (PMID 39826326, 2025). "Moreover, the downregulation of EGR1 was not only observed in adenocarcinoma but also B[a]P-treated mice adenoma, indicating that EGR1 reduction could be the early event in B[a]P-induced tumorigenesis." (PMID 34497759, 2021). "By conducting bioinformatic analysis on data from GEO databases, we observed upregulation of EGR1 in CRC tissues compared to that in normal mucosa and adenoma." (PMID 40190348, 2025). "•EGR1 mediates RSL3-related oxidative stress in adrenocortical cells and adenomas." (PMID 39826326, 2025).
anemia (3 papers, 2013 to 2025). A reduction in the number of red blood cells, the amount of hemoglobin, and/or the volume of packed red blood cells. "EGR1−/− or EGR1−/+ mice treated with phenylhydrazine develop anemia and are unable to be cured of their anemic condition." (PMID 41440765, 2025). "EGR1−/− mice treated with the DNA alkylating agent, N-ethyl-nitrosourea, develop immature T-cell lymphomas or myeloproliferative disorders, characterized by elevated WBC, anemia with ineffective erythropoiesis and thrombocytopenia." (PMID 41440765, 2025).
anxiety disorder (3 papers, 2012 to 2017). A category of psychiatric disorders which are characterized by anxious feelings or fear often accompanied by physical symptoms associated with anxiety. "Previous studies imply that the abnormality of certain genes is associated with anxiety disorders, such as CRHR1, FKBP5, CREB, Egr-1, Glo1, Gsr, AC8, CaMKIV, dystrophin, HTTLPR and COMT Met158." (PMID 22681774, 2012).
Arthritis (3 papers, 2012 to 2021). Inflammation of a joint. "Several studies have suggested roles for Egr-1 in the regulation of several genes involved in the pathogenesis of arthritis." (PMID 22455954, 2012). "Interestingly, EGR1 is directly involved in TNF-α mediated upregulation of prostaglandin E2 leading to inflammation and arthritis." (PMID 23140489, 2012).
chronic kidney disease (3 papers, 2021 to 2023). Impairment of the renal function secondary to chronic kidney damage persisting for three or more months. "Beyond CKD, persistent expression of EGR1 aggravates nephrotic progression, which has also been reported in many other chronic kidney diseases, such as unilateral ureteral obstruction 48 and proteinuric kidney diseases." (PMID 35910788, 2022).
dermatitis (3 papers, 2016 to 2025). An inflammatory process affecting the skin. "Indeed, SSA ameliorates AD-like skin inflammation by reducing EGR1-mediated TSLP expression in HaCaT keratinocytes; however, the effect of SSA on the expression of FLG remains unclear." (PMID 39274912, 2024). "β-Caryophyllene (BCP)—a selective CB2 agonist—ameliorates DNCB-induced AD-like dermatitis and downregulates keratinocyte TSLP/EGR1, supporting antipruritic and anti-inflammatory actions consistent with our cytokine trends." (PMID 41471858, 2025).
head and neck squamous cell carcinoma (3 papers, 2019 to 2023). A squamous cell carcinoma that arises from any of the following anatomic sites: lip and oral cavity, nasal cavity, paranasal sinuses, pharynx, larynx, and salivary glands. "Therefore, we evaluated how the NAB2-mediated suppression of EGR1 facilitates head and neck squamous cell carcinoma (HNSCC) cancer progression, in association with Sp1, which competes with EGR1 as a transcriptional regulator." (PMID 30845713, 2019). "Oxytocin has been demonstrated to increase Egr-1 expression via an EGFR- and ERK-dependent pathway in head and neck squamous cell carcinoma, which may inhibit tumor invasion and metastasis by promoting E-cadherin overexpression." (PMID 37046823, 2023).
hepatic (3 papers, 2023 to 2025). "Infection of astrocytes with Rift Valley fever virus (RVFV), a hemorrhagic fever virus known to induce significant hepatitis and encephalitis, induced a robust induction of EGR1 mRNA." (PMID 40789964, 2025). "Egr1 depletion exacerbated, rather than attenuated, carbon tetrachloride-induced hepatic fibrosis." (PMID 37587150, 2023).
hilar cholangiocarcinoma (3 papers, 2015 to 2020). A cholangiocarcinoma that arises from the junction, or adjacent to the junction, of the right and left hepatic ducts. "Expression of UCHL1, SNAT1, and EGR1 proteins was predominantly localized to the cytoplasm and was observed in 55.1% (27/49), 55.1% (27/49), and 44.9% (22/49) of hilar cholangiocarcinoma samples, respectively." (PMID 25971332, 2015). "A recent study reported that PRR11 signals could significantly induce the expression of EGR1 gene in patients diagnosed with hilar cholangiocarcinoma patients." (PMID 33276775, 2020). "Furthermore, the expression of EGR1 was decreased by silencing PRR11, which has oncogenic effects in hilar cholangiocarcinoma." (PMID 27835650, 2016).
Hodgkins lymphoma (3 papers, 2017 to 2023). A heterogeneous group of malignant lymphoid neoplasms of B-cell origin characterized histologically by the presence of Hodgkin and Reed-Sternberg (HRS) cells in the vast majority of cases. "High mGluR5-expression was associated with upregulation of PI3K/AKT and MAPK pathways and of downstream targets (e.g., EGR1) known to be involved in classical Hodgkin lymphoma progression." (PMID 36831273, 2023). "The blockage of Hodgkin’s lymphoma cells from entering into the EBV lytic cycle also occurs through the suppression of Egr-1." (PMID 29207655, 2017).
infertile (3 papers, 2017 to 2022). "For example, Egr1 regulates luteinizing hormone (LH) β expression, and female Egr1-knockout mice are infertile." (PMID 28464846, 2017). "EGR1 can regulate follicle development in the ovary, and the knockout of this gene significantly reduces the number of corpus luteum and the levels of progesterone and LHβ, resulting in infertility." (PMID 36359113, 2022). "Egr1 null female mice are infertile and lack expression of Lhb24." (PMID 31882740, 2019).
ischemic stroke (3 papers, 2020 to 2021). A stroke disorder caused by obstruction of blood flow to the brain, due to thrombotic (local blood clot formation) or embolic (due to a blood clot or other material traveling from another site) event. "PPARG plays an important role in the inflammatory response after ischemic stroke and can target EGR-1 to inhibit the inflammatory response after ischemic stroke, and its activation inhibition can increase M2 and decrease M1 microglia/macrophage." (PMID 34603472, 2021). "A research reported that cerebral microvascular endothelial cells displayed less apoptosis levels through microRNA-199b-3p via downregulating MAPK/ERK/EGR1 axis in ischemic stroke." (PMID 34227902, 2021). "Egr1 upregulated in MCAO mice in this study which was reported sharply increased after ischemic stroke." (PMID 33414894, 2020). "The study indicated that miR-199b-3p up-regulation could inhibit the apoptosis of cerebral microvascular endothelial cells by blocking MAPK/ERK/EGR1 axis, thus protecting mice from ischemic stroke." (PMID 34227902, 2021).
left ventricular hypertrophy (3 papers, 2022 to 2025). Enlargement of the LEFT VENTRICLE of the heart. "A high-fiber diet has notably been shown to decrease systolic and diastolic blood pressure, cardiac fibrosis, and left ventricular hypertrophy, partly through the down-regulation of Egr-1 in the heart and kidneys." (PMID 40821112, 2025). "A high-fiber diet and acetate supplementation significantly reduced blood pressures, cardiac fibrosis, and left ventricular hypertrophy through the downregulation of early growth response 1 (Egr1)." (PMID 36830978, 2023).
metastatic tumor (3 papers, 2019 to 2025). "We detected the expression of CD44 in tumor cells of the metastases by multiple immunofluorescences and analyzed the correlation between EGR1 and CD44 in the tumor components of the metastatic tumor (mesothelial cells were positioned by HBME1)." (PMID 38385088, 2024). "Furthermore, the levels of lncRNAs as well as EGR1 and CXCR4 were greater in patients with metastatic disease than in patients with localized disease." (PMID 40635521, 2025). "The expression of EGR1 in the metastatic mesothelial cells was detected by multiple immunofluorescences The correlation between EGR1 and HOXA11 in the cancerous components of the metastatic tumor was analyzed (mesothelial cells were positioned by HBME1)." (PMID 38385088, 2024).
mood disorder (3 papers, 2017 to 2023). A cognitive disorder a disturbance in which the person's mood is hypothesized to be the main underlying feature. "Egr-3, which colocalizes with Egr-1 and is also induced in an activity-dependent manner, has recently been implicated in multiple mood disorders." (PMID 28503137, 2017).
multiple sclerosis (3 papers, 2022 to 2025). A progressive autoimmune disorder affecting the central nervous system resulting in demyelination. "Importantly, in CD4+ T cells of multiple sclerosis patients, both Egr-1 and Foxp3 were found to decrease." (PMID 40235598, 2025).
myeloid neoplasm (3 papers, 2011 to 2020). Proliferation of myeloid cells originating from a primitive stem cell. "Haploinsufficiency of EGR1 cooperates with other mutations in the development of murine myeloid neoplasms, suggesting it might play a significant role in malignant transformation of stem cells leading to t-MNs." (PMID 28081176, 2017). "Of note is that the incidence of myeloid disease is higher in Egr1+/− mice (68%) than in WT mice (49%), indicating that loss of one allele of Egr1 shifts the disease spectrum from the more common lymphoid neoplasm to myeloid neoplasms." (PMID 21713073, 2011). "Hence the observation that 5q chromosome aberration that includes loss of one Egr1 allele is associated with t-MNs suggests that haploinsufficiency of EGR1 may cooperate with other mutations in the development of myeloid malignancies." (PMID 28081176, 2017). "Since resistance to apoptosis is a hallmark of malignant transformation, we investigated the role of EGR1 in apoptosis of bone marrow cells; a cell population from which myeloid malignancies arise." (PMID 28081176, 2017). "To identify cooperating cancer genes, we have cloned over 1500 retroviral integrations from myeloid neoplasms developing in 11 Egr1 WT and 19 Egr1+/− mice." (PMID 21713073, 2011). "The data presented here indicate that EGR1 may not significantly regulate the aberrant apoptosis response of hematopoietic stem and progenitor cells in myeloid malignancies." (PMID 28081176, 2017).
non-alcoholic fatty liver disease (3 papers, 2020 to 2024). "Knockout experiments on mice show that hepatocyte EGR1 helps maintain hepatic insulin response, and as a result, the loss of EGR1 in hepatocytes can contribute to liver steatosis leading to non-alcoholic fatty liver disease development." (PMID 32541819, 2020).
pituitary adenoma (3 papers, 2014 to 2019). "The PPI network of the downregulated DEGs in pituitary adenoma exhibited centralization, and certain node proteins of the network, including EGR1, STAT3, JUNB and FOS, were the common transcription factors in cancer; the PPI network of upregulated DEGs was sparsely populated." (PMID 25360166, 2014). "Thus, BRC induces apoptosis in rat pituitary adenoma cells through the ERK/EGR1 pathway." (PMID 31000722, 2019). "After siRNA transfection was used to downregulate EGR-1, the inhibitory effect of BRC on the proliferation of rat pituitary adenoma cells was weakened." (PMID 31000722, 2019).
preeclampsia (3 papers, 2018 to 2024). Preeclampsia is a hypertensive disorder of pregnancy that is characterized by new-onset hypertension with proteinuria presenting after 20 weeks of gestation, and depending on mild or severe forms may initially present with severe headache, visual disturbances, and hyperreflexia. "miR-518b, which is abnormally expressed in placental tissues during preeclampsia, not only regulates early growth response 1 (EGR1)-mediated angiogenesis and migration of trophoblast cells, but also regulates the establishment of the hypoxia model of early embryonic development." (PMID 35246136, 2022). "Moreover, levels of p-ERK, EGR1 and VEGF-A in placental tissue were lower in the preeclampsia group than in controls." (PMID 39619154, 2024).
renal carcinoma (3 papers, 2012 to 2023). A carcinoma arising from the epithelium of the renal parenchyma or the renal pelvis. "EGR1 has been implicated as an important factor in nephrogenesis and the development of renal cancer." (PMID 23029358, 2012). "Furthermore, EGR1 has been implicated as an important factor in nephrogenesis and the development of renal cancer." (PMID 36888606, 2023). "To assess the therapeutic effect of miR-192 in renal cancer, we injected A498 renal cancer cells expressing an EV or both EGR1 and HOXB9 (A498-EV and A498-EGR1+HOXB9, respectively) into the subcapsular space in the kidneys of mice." (PMID 27041221, 2016). "This miR-192-mediated anti-angiogenic effect was significantly reduced following the rescue of EGR1 and/or HOXB9 levels by lentiviral transduction in these renal cancer cells." (PMID 27041221, 2016).